PGF (placental growth factor)
Diseases named in the same sentence as PGF in open-access papers (continued):
Sharing a sentence is not in itself a finding about the gene and the disease.
pituitary tumor (1 paper, 2022). A benign or malignant neoplasm affecting the pituitary gland. "Compared with normal pituitary tissue, genes with the highest to lowest expression levels in pituitary tumor tissue were VEGFC (19.3-fold, p<0.0001), PGF (13.4-fold, p<0.0001), VEGFA (4.2-fold, p<0.0001) and VEGFB (2.2-fold, p=0.002)." (PMID 35600354, 2022). "Pituitary tumors also expressed significantly higher levels of angiogenesis growth factors, including VEGFA (4.2-fold), VEGFB (2.2), VEGFC (19.3), PGF (13.4), ANGPT2 (9.2), PDGFA (2.7), PDGFB (10.5) and TGFB1 (3.8) compared to normal pituitary tissue." (PMID 35600354, 2022). "This suggests that PGF and VEGFC are the main angiogenic growth factors initiating angiogenesis in human pituitary tumors." (PMID 35600354, 2022). "In addition, we identified PGF and VEGFC as the major angiogenic growth factors regulating angiogenesis in human pituitary tumors." (PMID 35600354, 2022). "Angiogenesis in pituitary tumors is regulated mainly by PGF and VEGFC, not VEGFA and VEGFB." (PMID 35600354, 2022). "Furthermore, we identified PGF and VEGFC, but not VEGFA or VEGFB, as the major angiogenic growth factors regulating angiogenesis in human pituitary tumors." (PMID 35600354, 2022).
Polypoidal choroidal vasculopathy (1 paper, 2024). The presence of aneurysmal 'polypoidal' lesions in the choroidal vasculature. "Aflibercept captures VEGF-A, VEGF-B and placental growth factor (PlGF), thereby improving the visual acuity and macular morphology in a large number of treatment-naive eyes with polypoidal choroidal vasculopathy (PCV)." (PMID 37728589, 2024).
prostate tumors (1 paper, 2013). "The primary stromal cell type found in prostate tumors is the carcinoma-associated fibroblast, which produces placental growth factor (PlGF)." (PMID 24005860, 2013).
Sensory neuropathy (1 paper, 2013). Peripheral neuropathy affecting the sensory nerves. "We previously used streptozotocin (STZ)-induced diabetic ddY mice with sensory neuropathy to evaluate the therapeutic effects of vascular endothelial growth factor and placental growth factor isoforms." (PMID 23407314, 2013). "We previously used streptozotocin (STZ)-induced diabetic ddY mice with sensory neuropathy to evaluate the potential therapeutic effects of vascular endothelial growth factor and placental growth factor isoforms." (PMID 23407314, 2013).
tumor (396 papers, 2002 to 2026). "The data analysis included PGF gene function, molecular pathway, protein interaction, gene expression and mutation across cancer type, survival prognosis and tumor immune infiltration association with PGF." (PMID 37508400, 2023). "We analyzed PGF gene function, molecular pathways, protein interactions, gene expression, mutations, survival prognosis, and tumor immune infiltration associated with PGF." (PMID 37508400, 2023). "In order to elucidate the role of the signature genes’ biological functions, the association of STMN1, RAP1A, FLT3, HSPA8, ANGPT2, and PGF was positively associated with tumor purity in HCC." (PMID 34178637, 2021). "Some studies have shown that tumor-secreted vascular endothelial growth factor (VEGF) as well as placental growth factor (PlGF) act by the retinal VEGF receptor 1 and induce loss of pericytes within the retinal vasculature (breaking the blood–retinal barrier)." (PMID 33182708, 2020). "Subsequently, stratification analysis by tumor stage showed that the risk effect for PGF rs8019391 appeared to be more prominent in the subset of patients with stage III + IV." (PMID 33109108, 2020). "This included genes in which upregulation is implicated in cancer (CTDSP2, CASC3, PGF) and those that are thought to be involved in tumor suppression (SASH1, HIPK2)." (PMID 23406646, 2013). "VEGFR1 is a receptor not only for VEGF, but also for placental growth factor (PGF), and is associated with tumour progression and neovascularization." (PMID 17486129, 2007). "Our findings showed the associations between the high expression of VEGFA, VEGFC, and PGF and poor prognosis across various cancers, suggesting that they may serve as risk factors for tumor progression." (PMID 37852616, 2023). "The overall evaluation was conducted given the totality of evidence, to target the PGF gene to treat the cancer where the PGF level was highly expressed in a certain tumor type with poor survival prognosis as well as possibly associated with poor tumor infiltration level." (PMID 37508400, 2023). "In this process, insulin-like growth factor-I (IGF-I) causes self-renewal of NSCLC cancer stem cells, followed by an increase in CXCL1 and placental growth factor (PlGF) expression in these cells, leading to angiogenesis and recurrence of the tumor." (PMID 38673949, 2024). "Apart from VM, the expression of key angiogenic factors such as angiopoietins, VEGF, and Placental Growth Factor (PGF), which are crucial for spiral artery remodeling in placentation and tumor cell growth, is a critical step for increasing blood supply." (PMID 38707901, 2024). "Angiogenesis under different conditions, including tumor pathogenesis, is regulated by VEGF, a gene family that includes several VEGF variants such as VEGFA, B, C and D, alongside placental growth factor (PGF)." (PMID 38816668, 2024). "The overexpression of PGF has been reported to lead to the inhibition of angiogenesis and the normalization of blood vessels, which in turn suppresses tumor growth." (PMID 39628692, 2024). "Across tumor stages, VEGFA, VEGFC, and PGF exhibited an increasing expression tendency as the tumor stage advanced." (PMID 37852616, 2023). "Placental growth factor (PLGF) is a pro-angiogenic factor belonging to the VEGF family, whose overexpression has been observed in several tumor-resistant to anti-angiogenic therapies, making PLGF a potential HCC therapeutic target." (PMID 36769116, 2023). "Placental growth factor (PlGF), which is significantly associated with CD90 expression, was significantly correlated, and high levels of both PlGF and CD90 were associated with tumor angiogenic markers (CD31, CD34, and CD105." (PMID 36747131, 2023). "The proteins secreted by the primary tumor, VEGF, and placental growth factor (PIGF) affect the bone marrow mesenchymal stem cells, causing the BMDCs to go to the preferred site for metastasis before the disseminated tumor cells do." (PMID 37174117, 2023).
tumor (continued). "For example, treatment of tumor-bearing mice with VEGF neutralizing antibodies resulted in significant induction of placental growth factor, PlGF." (PMID 37060495, 2023). "The expression of the placental growth factor (PGF) in cancer cells and the tumor microenvironment can contribute to the induction of angiogenesis, supporting cancer cell metabolism by ensuring an adequate blood supply." (PMID 37508400, 2023). "As the member of the VEGF family, PGF can bind to VEGFR1 to promote tumor angiogenesis and growth, and inhibition of PGF expression can reduce the metastasis and growth of a variety of tumors." (PMID 36776357, 2022). "Another application of tumor-specific nanobodies is targeting the tumor-associated ligands such as VEGF and placental growth factor (PlGF)." (PMID 35656179, 2022). "Polymeric NPs can be loaded with siRNAs to target vascular endothelial growth factor and placental growth factor signaling in both tumor cells and M2 TAMs, skewing the immunosuppressive M2 TAMs to the M1 type and thereby inhibiting tumor growth." (PMID 35296338, 2022). "PEA or AM11095 inhibited the secretion of IL-6 and IL-8, reduced the activation of the NF-kB pathway, decreased the expression of VEGF and Placental growth factor (PLGF) in TNBCs, and inhibited tumor cell migration in vitro." (PMID 36564457, 2022). "Placental growth factor (PlGF), another member of the VEGF family, also promotes tumor-associated macrophage (TAM) repolarization to the M2 subtype." (PMID 36013403, 2022). "Placental growth factor (PGF) is another protein known to promote angiogenesis in the tumor microenvironment by stimulating the VEGF pathways." (PMID 35163279, 2022). "With regard to molecular structure, ECs of tumor tissues have been reported to highly express Placental growth factor (PlGF), CD137, CD109, and CD276." (PMID 33685452, 2021). "Functional studies have attributed a role for SHH ligand‐dependent stimulation of tumor stromal secretion of placental growth factor (PGF) and neuropilin (NRP) in SHH‐MB development." (PMID 33469989, 2021). "It has been demonstrated that histidine-rich glycoprotein (HRG) can downregulate placental growth factor (PlGF) levels, leading to the restoration of tumor vessel functionality and TAM repolarization." (PMID 34603327, 2021). "When inhibited, pro-angiogenic factors, such as vascular-endothelial growth factor (VEGF), placental growth factor and aniopoietin-2, are downregulated, preventing blood supply and nutrition to the tumour cells, thus inhibiting tumour growth and spread." (PMID 33802014, 2021). "As well, a VEGF homolog, placental growth factor (PlGF), is expressed and secreted by both bone-resident cells and tumor cells." (PMID 33805598, 2021). "Its activation by VEGF‐A or placental growth factor (PlGF) promotes tumour cell survival, migration and invasiveness." (PMID 31758648, 2020). "Nevertheless, we propose the VEGF ligands/receptors interplay (unbalanced in AFP-high tumours due to VEGFB/PGF overexpression) as a rationale for the enhanced activation of the VEGF pathway and thus the efficacy of ramucirumab in AFP-high HCC3." (PMID 31285588, 2019). "The vascular endothelial growth factor (VEGF) family consists of VEGF-A, -B, -C, -D, -E, -F and placental growth factor (PlGF), which have been identified as specific angiogenic and lymphangiogenic factors in tumor progression and metastasis." (PMID 27901498, 2017). "GPR64 promotes tumor invasion and metastasis through induction of the placental growth factor (PGF) and metalloproteinase (MMP1) expression." (PMID 28694502, 2017). "Histidine-rich glycoprotein repolarizes M2-like TAMs to enhance anti-tumor immune responses and vessel normalization via downregulation of placental growth factor (PlGF)." (PMID 28467800, 2017).
tumor (continued). "Tumor cells can develop treatment resistance via upregulation of pro-angiogenic signals (e.g., placental growth factor or fibroblast growth factor) or by increased expression of protective pericytes that express the platelet-derived growth factor receptor." (PMID 29245960, 2017). "Some of the growth factors implicated in tumor vascularization include vascular endothelial growth factor (VEGF), placental growth factor (PlGF), fibroblast growth factor (FGF) and hepatocyte growth factor (HGF)." (PMID 27626690, 2016). "Members of the VEGF family and the placental growth factor PlGF have been characterised as angiogenesis modulators in many tumours." (PMID 28105072, 2016). "Placental growth factor levels in plasma and tumours correlate with tumour stage, vascularity, recurrence, metastasis, and survival in various tumour diseases." (PMID 22333707, 2012). "Apparent tumor formation was observed in mGF-iPS-3F- and pGF-iPS-4F-injected mice at weeks seven and ten after injection, respectively." (PMID 20856871, 2010). "In non-tumor bearing animals, monocyte and macrophage migration is driven in part by placental growth factor (PlGF), VEGF and VEGFR1." (PMID 19888452, 2009). "A remarkable micro array study of placental expression patterns revealed a rich diversity of tissue and function restrictions and overexpression of placental growth factor (PlGF) in cell culture seemed to inhibit tumor growth in a mouse model." (PMID 19698096, 2009). "Absolute placental growth factor (PlGF) levels were low at baseline in both groups, followed by a strong induction in the responders at week 3 and a return to low levels after treatment ended and the tumour was resected." (PMID 40295487, 2025). "Among the many factors involved in this intricate crosstalk, which could support tumor growth and progression, an important role could be played by the angiogenic factor, i.e., placental growth factor (PlGF)." (PMID 39457506, 2024). "Since PGF expression increases locally in the tumor milieu upon PARPi treatment, it is possible that a minor subpopulation of Brca1- and Bard1-deficient tumor cells that express the PGF receptor FLT1 prior to PARPi treatment becomes enriched in the PARPi-resistant tumors." (PMID 38956205, 2024). "In addition, cluster 25 relates to the regulation of VEGF-induced migration, including the expression of key VEGF-related genes (NRP1, NRP2, FLT1, KDR, PGF), which can promote tumour dissemination by supporting the invasion of malignant cells into the stroma." (PMID 38331751, 2024). "Finally, VEGF or Placental Growth Factor (PlGF) are also able to induce the recruitment and survival of monocytes in the tumor micro-environment." (PMID 37143666, 2023). "In KIRP, VEGFA, VEGFC, and PGF were differentially expressed across tumor stages." (PMID 37852616, 2023). "Another evidence for the correlation between tumor progression and angiogenic markers came from the finding that overexpression of placental growth factor (PlGF), another member of the VEGF family in stages IIB and IVA1 lesional skin of MF, has been linked with CCL27 and IL-4 expression." (PMID 37746258, 2023). "The VEGF receptor pathway is crucial in tumour angiogenesis and consists of 5 related ligands, namely placental growth factor (PlGF), VEGF A, VEGF B, VEGF C, and VEGF D which differentially bind to three receptor tyrosine kinases (VEGF R1, VEGF R2, and VEGF R3)." (PMID 35563045, 2022). "Growing evidence implicates a role for neuropilin-1 in promoting cancer progression by acting as a co-receptor for molecules involved in the EMT pathway and metastasis in tumor tissue such as vascular endothelial growth factor, placental growth factor, and TGF-β1." (PMID 35303925, 2022).
tumor (continued). "The Insulin signaling pathway in group 5 was found to mainly lead to activation of genes involved MAPK signaling and this trend converges with hypoxia signaling input, both leading to the production of VEGFB, VEGFA, PGF, growth factors known to be involved in angiogenesis and tumor invasion." (PMID 35568708, 2022). "Particularly, tumor-infiltrating NK cells expressed higher levels of VEGF, IL-8, matrix metallopeptidase 9 (MMP9), placental growth factor (PlGF) and angiogenin, which, collectively participate in tumor angiogenesis, tumor microenvironment remodeling and tumor growth." (PMID 34445750, 2021). "Moreover, histidine-rich glycoprotein was able to repolarise M2-like TAMs to M1-like TAMs with elevated tumour immunity and mediated vascular normalisation via downregulation of placental growth factor (PlGF)." (PMID 33917287, 2021). "In addition, the overexpression of PGF is correlated with tumor stage, cancer progression and metastasis." (PMID 33109108, 2020). "Importantly, tumor-associated antigens such as 5-lipoxygenase (breast cancer; and placental growth factor (glioblastoma; have been shown to induce IL-10-production in tumor-infiltrating B cells in murine models." (PMID 33569063, 2020). "The formation of tumor blood vessels from existing ones, called angiogenesis, occurs in response to the proangiogenic stimuli, including VEGF, basic fibroblast growth factor (bFGF), placental growth factor, and angiopoietin, among others that are produced by the tumor cells." (PMID 31600937, 2019). "These cells express VLA-4(α4β1), which are recruited and mobilized by tumour-derived secreted factors such as placental growth factors (PlGF) and VEGF-A to activate resident fibroblast in the metastasis niche to prime the metastatic site in lung rich with fibronectins." (PMID 29506506, 2018). "However, the analysis of the difference in the mRNA expression levels between normal and tumor tissue indicated that the greater the expression level of placental growth factor (PGF) in tumor relative to normal tissue, the greater is the chance for recurrence." (PMID 25575813, 2015). "Notably, the set of the most influential HSC regulators included several well-known tumor-promoting genes such as placental growth factor (PGF), and the chemokine CXCL1, which promotes HCC angiogenesis and growth." (PMID 26020769, 2015). "It has been suggested that other proangiogenic factors such as placental growth factor (PlGF) could also participate in tumor-induced immunosuppression." (PMID 26000020, 2015). "Other pro-angiogenic factors such as placental growth factor (PlGF) could also participate in tumor-induced immunosuppression, but only few works have been performed on this point." (PMID 24765614, 2014). "Additional angiogenic factors such as the placental growth factor (PlGF) directly or indirectly stimulate angiogenesis by affecting a wide range of different cell types or by attracting MDSCs and macrophages within the tumor microenvironment (TME)." (PMID 25136356, 2014). "Lower PGF expression in White patients might correlate with a less aggressive tumor phenotype." (PMID 40558258, 2025). "Also, in up to 75% of cases, tumor growth may occur due to the production of growth factors such as the placental growth factor, insulin-like growth factor and vascular endothelial growth factor, all of which promote tumor angiogenesis." (PMID 40041218, 2022). "Additionally, COL18A1 and PGF were screened as tumor cell hub ligands in branches I and II." (PMID 33971970, 2021). "The factors, such as vascular endothelial growth factor (VEGF), and placental growth factor (PlGF), released by the primary tumor act on the bone marrow mesenchymal stem cells to induce the BMDCs to reach the expected metastasis site before the disseminated tumor cells arrive." (PMID 33489906, 2020).